CD4 (CD4 molecule)
Diseases named in the same sentence as CD4 in open-access papers (continued):
Sharing a sentence is not in itself a finding about the gene and the disease.
AIDS (continued). "A swing from a Th1 to a Th2 cytokine pattern has been previously hypothesized to parallel or even precede the progressive CD4 impairment that accompanies the transition towards the final stage of AIDS." (PMID 31641392, 2019). "Stable reconstitution of CD4+ T-cell number and functional clonality, with complete suppression of viral replication and elimination of viral reservoirs, has been the ultimate goal of AIDS therapy." (PMID 31165736, 2019). "Thus, although HIV/AIDS patients take longer time to reach a normal CD4 cell count level than the time taken to reach a suppressed viral load count, once a normal CD4 cell count is reached mortality risks are reduced." (PMID 30770728, 2019). "Idiopathic AIDS symptoms such as parkinsonism, demyelination and arthritis could be explained by poor CD4+ T cell-mediated control of Malassezia populations in internal organs." (PMID 31396143, 2019). "Therefore, HIV/AIDS control effort should go beyond objective measures such as CD4 count and viral load, and lay more emphasis on improving the health-related quality of life (HRQoL) of PLH." (PMID 30606187, 2019). "It found that earlier ART (within 2 weeks of TB treatment initiation) reduced the rate of new AIDS defining illness or death (hereafter AIDS event) exclusively in persons with CD4 counts of less than 50 as compared with later ART (between 8 and 12 weeks after TB treatment initiation)." (PMID 30707696, 2019). "PDH is usually seen in AIDS patients with absolute CD4 counts of less than 150–200 cells/uL." (PMID 30791902, 2019). "SHIV89.6P, a SHIV generated by serial passage in macaques that was used frequently because it consistently showed a high level of early replication, rapid CD4+ lymphocyte depletion, and fast progression to an AIDS-like illness in macaques, provides a cautionary tale." (PMID 30943274, 2019). "Rates of new AIDS-defining illness or death at 48 weeks, by CD4+ count." (PMID 30707696, 2019). "A number of studies assessed the relationship between co-receptor tropism (CRT) and HIV disease progression; in particular, patients with a dual/mixed (DM) or X4 strain have a greater and a more rapid CD4 cell decline and progression to AIDS compared to persons with a R5 virus." (PMID 30818365, 2019). "Researchers in the US established a new prognosis scoring system (i.e., ARL IPI) by combining the HIV scores (prior history of AIDS, baseline CD4+ count, and viral load) with lymphoma prognostic factors and found that this system significantly better predicted the risk of death, compared to aaIPI29." (PMID 30926889, 2019). "However, viral load monitoring is a better predictor of HIV/AIDS progression than CD4 cell count and hence viral load is deemed superior." (PMID 30770728, 2019). "The aim is to determine whether CD4 cell count or viral load count can be used to model HIV/AIDS progression." (PMID 30770728, 2019). "In conclusion, HIV/AIDS patients on antiretroviral therapy were dropout in a short period due to patients marital status married and separated, primary education level, high level of CD4 count, being merchants, farmer and daily labour." (PMID 30999924, 2019). "The CD4/CD8 ratio has become an impressive marker for immune dysfunction among HIV-infected patients and, unlike the CD4 cell count, it can be used by clinicians to identify patients at risk of non-AIDS-related events." (PMID 30818365, 2019). "Acquired immunodeficiency syndrome (AIDS) is a life-threatening acquired disorder resulting from an infection with the human immunodeficiency virus (HIV) and the subsequent progressive loss of CD4+ T cells." (PMID 30787394, 2019). "Recent findings indicate that individual people living with HIV/AIDS (PLWHA) with lower levels of CD4 T-cell count below 200/mm3 tend to experience higher mean malaria parasite densities than their counterparts with higher CD4 T-cells counts." (PMID 31354844, 2019).
AIDS (continued). "This could explain the association of the early appearance of CXCR4-tropic virus with enhanced CD4+ cell depletion and progression to AIDS." (PMID 30761146, 2019). "We previously showed that administration of autologous bone marrow transfusion (BMT) via the hepatic portal vein could effectively restore CD4+ T-cell count in AIDS patients who were also suffering from decompensated liver cirrhosis." (PMID 31165736, 2019). "If true, our findings would be consistent with the concept that hosts who mount a stronger immune response against the infecting virus have greater numbers of positively selected sites and progress to AIDS at a lower rate, which is reflected by higher postseroconversion CD4+ T-cell levels." (PMID 30622192, 2019). "An alternative explanation for LoC could be a switch in the viral tropism from CCR5 to CXCR4, which has been described to precede a decrease in CD4 T-cell counts and progression to AIDS (37, –, 40)." (PMID 30487276, 2019). "In contrast to immunocompetent patients, where direct mycologic or histopathologic exams show poor sensitivity, in immunocompromised hosts these methods may depict higher sensitivity, especially in AIDS patients with very low CD4 cell counts." (PMID 30641918, 2019). "The selective survival and enrichment of CCR5-modified CD4+ T cells in humanized mice challenged with HIV-1 may provide the reference for reconstitute immune function in individuals with HIV-1/AIDS." (PMID 31186067, 2019). "In a multivariate Cox proportional hazard model, we found 7 predictors including LDH >350U/L, HR>130 times/min, room air PaO2 <70mmHg, later admission to ICU, Anemia (HGB≤90g/L), CD4<50cells/ul, and development of a pneumothorax were associated with poor prognosis in HIV/AIDS patients with PCP." (PMID 30906778, 2019). "The median time to AIDS from the first recorded CD4% value was 8.6 years (95% CI, 6.5 to 10.8 years) for faster progressors with a low combined coefficient and 18.7 years (95% CI, 13.6 to 23.8 years) for slower progressors with a high combined coefficient (P < 0.001 [log rank test])." (PMID 30622192, 2019). "Mortality from I. belli infection in HIV/AIDS is high, especially at low CD4 + levels." (PMID 32546916, 2019). "The 2016 World Health Organization guidelines recommending early ART initiation to all PLHIV irrespective of CD4 cell count were based on a growing body of evidence showing the increased risk of AIDS or death associated with delaying treatment." (PMID 30819120, 2019). "Furthermore, nearly 70% (78/112) met the criteria for AIDS (i.e., CD4 < 200 cells/μL) and over 50% (56/112) were severely immunosuppressed (i.e., CD4 < 100 cells/μL)." (PMID 31638941, 2019). "Implying weaken immunity caused by low CD4+ T cell count may contribute Blastocystis infection in HIV/AIDS patients, and it was reasonable that the HIV/AIDS cases should be receive standardized treatment and long-term monitoring." (PMID 31623666, 2019). "Furthermore, 53.9% of participants had a most recent CD4 cell count of < 350 and 18.6% had AIDS-related clinical symptoms." (PMID 31096967, 2019). "In most countries of the sub-Saharan Africa, the burden of intestinal parasites are increasing with the immergence of HIV/AIDS because the CD4 depletion and hematological abnormality secondary to HIV/AIDS predisposes opportunistic infections associated with intestinal parasites." (PMID 31029088, 2019). "We previously reported that autologous BMT via the hepatic portal vein could effectively reconstitute peripheral CD4+ T-cell counts and hepatic function in splenectomized AIDS patients with decompensated liver cirrhosis." (PMID 31165736, 2019). "During stage III and rarely during stage IV (while low CD4+ counts and AIDS are noted, respectively), CD8+ T-cell induced autoimmune disorders such as psoriasis and diffuse lymphocytic syndrome may occur." (PMID 33324890, 2019).
AIDS (continued). "We previously showed that autologous bone marrow transfusion (BMT) via the hepatic portal vein could effectively restore CD4+ T-cell count in AIDS patients also suffering from decompensated liver cirrhosis." (PMID 31165736, 2019). "Similarly, the atypical radiographic appearance of pulmonary TB is common in AIDS patients with CD4 T-lymphocytes count less than 200 cells/ μL." (PMID 30281631, 2018). "Early infections may then be misclassified as later infections, including some as stage 3 (AIDS) because low CD4 T-lymphocyte counts and opportunistic illnesses meeting criteria for stage 3 sometimes occur transiently in acute infection." (PMID 30401660, 2018). "Furthermore, the host’s CD4+ T cell count had an independent impact on the prognosis of AIDS patients with PTB." (PMID 29587840, 2018). "At diagnosis, with an average of 38 ± 13 years old, intravenous drug use being the major risk of transmission (62%), only one case of HIV type 2, 79% with the diagnosis of a concomitant AIDS‐defining illness and 62% were late presenters (CD4+ T lymphocyte count <200/mL)." (PMID 30362663, 2018). "These HIV particles target new CD4 cells resulting in the progression of HIV infection to AIDS." (PMID 29343268, 2018). "Patients who had initially been diagnosed with TB before commencement of ART recover better from HIV/AIDS disease except that transitions to death for patients with CD4 cell count between 350 and 500 cells/mm3 are two times higher than that of patients who were not initially diagnosed with TB." (PMID 29343268, 2018). "However, we previously reported that blockade of IFN-I signaling in rhesus macaques during acute SIV infection results in increased SIV reservoir size, accelerated CD4 T cell depletion and faster progression to AIDS." (PMID 30142226, 2018). "Additionally, we produced the paediatric estimates of HIV/AIDS mortality using the CD4 progression and CD4-specific mortality rates developed by UNAIDS." (PMID 30415748, 2018). "However, illustrations that explained the body and HIV were welcomed such as an image of an x-ray that revealed and explained Pneumocystis pneumonia as a complication for AIDS that required taking an antibiotic to prevent it when the CD4 count is low." (PMID 30064971, 2018). "In addition to a high conjugation rate, there was robust apoptosis of the HIV-positive CD4 T cells after incubation with autologous CD8 T cells in AIDS patients." (PMID 30254642, 2018). "The HIV, which causes acquired immunodeficiency syndrome (AIDS), induces dramatic CD4+ T cells loss during primary infection, which shows no district differences to general influenza." (PMID 30341241, 2018). "These generally include CD4 cell count and/or AIDS defining disease." (PMID 29970017, 2018). "We previously reported that the full length Nef protein and Nef peptides containing residues 50–60 (herein referred to as motif 1, M1) bind to CXCR4 and initiate the apoptotic program in CD4+ T cells which may contribute to the pathogenesis of AIDS in vivo." (PMID 29682200, 2018). "First, the peripheral CD4+ T cell count is a standard measure of disease progression in HIV-infected individuals, since a higher CD4+ T cell count is associated with a lower short-term risk of AIDS events and higher body mass index." (PMID 29703963, 2018). "We used a consensus definition of LP, relying on CD4+ T-cell count and AIDS-defining symptoms." (PMID 30401010, 2018). "In HIV patients, their frequency post-ART correlates with HIV-RNA, CD4+ T cell count, and immune activation markers, suggesting their pathogenic involvement in AIDS or non-AIDS related complications." (PMID 30459765, 2018). "Increased PLR has been linked to hypercholesterolemia and metabolic-syndrome, while high CD8+ cells count to increased risk of non-AIDS-related events regardless of CD4 T-cell recovery and to virological failure." (PMID 29940869, 2018).
AIDS (continued). "BHIVA Standards of Care (2013 and 2018) recommend that HIV services should review all patients presenting with CD4 <200 or AIDS diagnosis in order to identify potential missed opportunities (MOs) for HIV testing that could have avoided late diagnosis." (PMID 30362663, 2018). "We used a 7.5% rate so that an annual incidence of 1013 cases could be estimated (based on a 15% rate among newly presenting AIDS patients) and so that this presentation could be spread over two years for those with CD4 counts <200 × 106/mL." (PMID 29534500, 2018). "Clients with low CD4 counts might present with some AIDS symptoms and therefore need medical care, whereas those with high CD4 counts consider themselves well and do not feel the need to enrol in care." (PMID 30114244, 2018). "Similarly, PI‐based regimens and CD4 were predictive of virologic failure and AIDS was predictive of treatment modification only among younger patients." (PMID 29569354, 2018). "The CD4/CD8 ratio has been associated with the risk of AIDS and non-AIDS events." (PMID 29807541, 2018). "HIV/HCV-coinfected patients were more likely than those HIV-monoinfected to have acquired HIV through injecting drugs use, to be women, older at the start of ART, of Spanish origin with lower education level, and started ART with a lower CD4 count and an AIDS diagnosis." (PMID 30235668, 2018). "This could be highly possible since late presenters progress easily to advanced AIDS stage, a stage characterized by marked CD4 reduction, multiple comorbidities and poor overall functional status." (PMID 29378523, 2018). "This could be associated with the immune collapse and progression to AIDS, evidenced by the relationship found between HDL and CD4+ T-cells count or HIV RNA load." (PMID 29963050, 2018). "If infected but not on ARTs, CD4 levels decline thereby causing the immune system to weaken and resulting in progression to AIDS and death from AIDS related diseases." (PMID 30344234, 2018). "Patients were at the AIDS stage in 17% and 36% had a CD4 nadir <200/mm3." (PMID 30362663, 2018). "In high-income countries, HIV-infected adults with controlled infection and high CD4 cell counts currently live longer than ever before, and the main causes of morbidity and mortality have switched from AIDS-defining to non-AIDS-defining disorders." (PMID 30379870, 2018). "In addition, VCT center in Shiraz supplies free HAART (highly active anti-retroviral therapy), physician visit, and CD4 count test for all HIV/AIDS patients." (PMID 30602966, 2018). "In the case of C. neoformans, it is most commonly low CD4+ T cell count due to HIV/AIDS." (PMID 29463005, 2018). "Additionally, the infected CD4+ T cells die of apoptosis causing the CD4/CD8 T-cell inversion, the hallmark of all three AIDS-causing lentiviruses (HIV-1, FIV, and SIV)." (PMID 29789450, 2018). "For example, in HIV/AIDS studies, the trajectories of CD4 counts and time-to-death are collected." (PMID 29546067, 2018). "An inverted CD4:CD8 ratio (< 1) may be a biomarker for underlying immune activation and increased risk of non‐AIDS‐defining adverse events 3, 4, and can be derived from routinely measured clinical data." (PMID 30084150, 2018). "However, patients receiving InSTI‐based regimens had less severe disease, indicated by fewer baseline AIDS diagnoses (CD4 < 200/mm3 or CDC stage C) and lower HIV RNA levels than those on PI‐based and NNRTI‐based regimens." (PMID 30362663, 2018). "Additionally, the paediatric HIV/AIDS mortality estimates were produced with the CD4-count-specific mortality and progression parameters developed by UNAIDS." (PMID 30496103, 2018). "Over the 2000–2011 period, more than 50% of HIV-infected people were diagnosed late (defined as diagnosis with a CD4 count below 350 cells/μL or an AIDS diagnosis in the first 6 months after diagnosis) and a third presented very late (defined as diagnosis with a CD4 count below 200 cells/μL)." (PMID 30348140, 2018).
AIDS (continued). "The other subject initially presented the characteristic phenotype of an HLA-B*27:05/57:01-positive HIV-infected subject, with a low viral load (65 copies/ml) and high absolute CD4+ T cell count (950 cells/mm3), but within 2.7 years had progressed rapidly to AIDS (CD4+ T cell count < 200 cells/mm3)." (PMID 29338738, 2018). "The findings of this study show that double deletion of glutathione S-transferases M1 and T1 with normal CD4+ count in patients diagnosed with HIV/AIDS may be as a result of compensatory effect to reduce oxidative stress." (PMID 29795558, 2018). "This study revealed that subjects carrying the CRF01_AE subtype may suffer a faster loss of CD4 cells and earlier HIV/AIDS progression compared with those carrying a non-CRF01_AE subtype." (PMID 28484257, 2017). "As chronic progressors (CPs) or normal progressors (NPs), the majority of HIV-1-infected patients with progressive virus replication have chronic loss of CD4+ T cells and develop to AIDS in several years without any antiretroviral therapy (ART)." (PMID 28222782, 2017). "Indeed, Env has been shown to induce autophagy-dependent apoptosis of uninfected bystander CD4+ T cells, likely significantly contributing to AIDS pathogenesis by depleting the CD4+ T cell population." (PMID 28946621, 2017). "Time-dependent covariates were AIDS diagnosis, CD4 cell count, HIV RNA." (PMID 29202691, 2017). "18% had a history of AIDS at start of treatment and 13% had a CD4 cell count below 200/μL." (PMID 28207816, 2017). "This decline in the number of CD4+ cells indicates the development of HIV to AIDS." (PMID 28326304, 2017). "Importantly, cryptosporidiosis can be resolved in AIDS patients following restoration of their CD4+ T cell levels." (PMID 28800747, 2017). "Interestingly, different prognostic factors were found to be associated with death in NAE-free PLWH, including lower CD4 cell counts and higher HIV viral load at cohort engagement, previous AIDS diagnosis and HCV coinfection, besides older age." (PMID 28886092, 2017). "First, since all the participants are recruited from an internal HIV and AIDS clinic, their most current as well as future physiological lab values (eg, triglyceride levels, glucose levels, CD4+ lymphocyte count, HIV viral load) is easily accessed through the clinic’s medical database." (PMID 28446421, 2017). "If the infection is left untreated, the number of CD4+ T cells eventually falls below a critical level and the immunocompromised patient may die from AIDS-related complications." (PMID 28620380, 2017). "However, patients who dropped out had no significant clinical differences regarding the prevalence of baseline hyponatremia, CD4 count and AIDS." (PMID 28122494, 2017). "The CD4 count was ≤200 cells/mm3 (AIDS-defining) in 167/282 (59%) patients." (PMID 28348607, 2017). "Recently, joint modeling has been used frequently to evaluate the associations between longitudinal and time-to-event data such as CD4 count and survival in AIDS studies; urine measurements and acute kidney injury after surgery; and IgG antibody titer and recurrence of pemphigus." (PMID 28924464, 2017). "When this returned positive, a CD4 count was obtained and showed 3 cells/mm3, confirming AIDS." (PMID 28890836, 2017). "Similarly, level of viremia during acute HIV infection, setpoint viral load, rate of CD4+ T cell depletion, and eventual rates of progression to AIDS all vary widely." (PMID 28695282, 2017). "The median nadir CD4+T was 108 cells/μl, and 41% had AIDS diagnosis." (PMID 28388647, 2017). "These phenotypic and functional differences of CD4+ T cells in children, in addition to reported age-related declines of CD4+ T cells, further complicate interpretations about the impact of CD4+ T cell infection in pediatric cases that progress more rapidly to AIDS." (PMID 29259605, 2017).